ATF3 (activating transcription factor 3)
Diseases named in the same sentence as ATF3 in open-access papers (continued):
Sharing a sentence is not in itself a finding about the gene and the disease.
prostate tumours (4 papers, 2011 to 2025). "Given the potential tumour suppressor roles of DUSP1, FOS, and ATF3, we compared the expression of these genes in prostate tumours and benign prostate tissue." (PMID 40725480, 2025). "Here we employed systems analysis to identify genome-wide targets of ATF3 that is either induced by an alkylating agent methyl methanesulfonate (MMS) or over-expressed in a prostate tumour cell line LNCaP." (PMID 22046379, 2011). "Similarly, we also observed Fra1/2, Atf3, JunB and AP-1 binding sites are enriched in predominantly Gleason pattern 3 tumours as compared to higher grade prostate tumours." (PMID 34911933, 2021). "In the context of prostate tumor development and progression, we speculate that the epigenetic suppression of ATF3 by EZH2 by might be an important protective mechanism that promotes survival as tumors develop/progress and are subject to increasing cellular and environmental insults." (PMID 37104245, 2023). "In this analysis of HOX gene expression in prostate tumours and matched benign tissue, we have identified a subset of 14 HOX genes, DFA3_HOX, the expression of which is negatively correlated with ATF3, DUSP1, and Fos." (PMID 40725480, 2025). "In this bioinformatic analysis, we have identified HOX genes that show a negative correlation with Fos, DUSP1, and ATF3 expression in prostate tumours." (PMID 40725480, 2025).
rheumatoid arthritis (4 papers, 2020 to 2024). A chronic, systemic autoimmune disorder characterized by inflammation in the synovial membranes and articular surfaces. "ATF3 is not detectable in intact primary sensory neurons but is upregulated in the nucleus of injured peripheral neurons, such as in rheumatoid arthritis and OA mouse models, suggesting the presence of primary afferent injury." (PMID 36359375, 2022).
bone cancer (3 papers, 2010 to 2022). A primary or metastatic malignant neoplasm affecting the bone or articular cartilage. "As previously observed in rat sensory and motor neurons following spinal and sciatic nerve injury and recently in mouse bone cancer models, ATF-3 was shown to be up-regulated in DRG neuron somas 14 days after tumor implantation." (PMID 21048940, 2010).
brain injury (3 papers, 2024 to 2026). Acute and chronic (see also brain INJURIES, CHRONIC) injuries to the brain, including the cerebral hemispheres, CEREBELLUM, and brain STEM. "Activating transcription factor 3 (ATF3) is a neuroprotective factor and participates in acute brain injury." (PMID 41250979, 2025). "It is noteworthy that serum ATF3 remains unchanged in peripheral trauma patients without spinal cord or brain injuries, indicating that serum ATF3 serves as a biomarker for CNS injuries." (PMID 38649772, 2024).
brain tumor (3 papers, 2017 to 2025). "Gene profiling revealed that BV2 cells expressed higher levels of both M2‐associated genes (Maf, Selenop, P2ry14, Mrc1, Ctsc, and Cxcr4) and M1‐associated genes (Il7r, Atf3, and Gadd45g) compared to RAW264.7 cells, suggesting its multifaceted role in interaction with brain tumors." (PMID 40747560, 2025). "To test this hypothesis, we first analyzed ATF3 protein expression in HRasV12/TRIM24 brain tumor xenografts and clinical Ep‐GBM samples." (PMID 38828688, 2024). "However, treatment with Dabrafenib significantly decreased the tumor burden, extended the overall survival of animals bearing NHA/HRasV12/TRIM24 brain tumor xenografts (P < 0.01), and reduced tumor Ki‐67 and ATF3 protein expression." (PMID 38828688, 2024).
cerebral infarction (3 papers, 2023 to 2025). An ischemic condition of the brain, producing a persistent focal neurological deficit in the area of distribution of the cerebral arteries. "Cerebral infarction of rats was alleviated by lv-ATF3 compared with lv-NC rats (p < 0.01), but administration of anisomycin significantly increased infarct area compared with lv-ATF3 rats (p < 0.01)." (PMID 40621504, 2025). "With the gain-of-function approach, administration of Ad-ATF3 48 h before transient MCA occlusion was shown to attenuate brain infarct." (PMID 36768628, 2023). "With the gain-of-function approach, both pre- and post-ischemic administration of Ad-ATF3 ameliorated brain infarct and neurological deficits." (PMID 36768628, 2023).
cholangiocarcinoma (3 papers, 2019 to 2021). A carcinoma that arises from the intrahepatic biliary tree (intrahepatic cholangiocarcinoma) or from the junction, or adjacent to the junction, of the right and left hepatic ducts (hilar cholangiocarcinoma). "The differentially expressed mRNAs in cholangiocarcinoma (CC) and its adjacent tissues were screened by microarray analysis, and the expression of ATF3 was detected through Quantitative real time polymerase chain reaction (qRT‐PCR) and Western blot." (PMID 30648816, 2019). "The results revealed that ATF3 expression was lower in bladder urothelial carcinoma (BLCA), breast invasive carcinoma (BRCA), cholangiocarcinoma (CHOL), kidney chromophobe (KICH), and liver hepatocellular carcinoma (LIHC) cancer patients." (PMID 33407456, 2021).
chronic kidney disease (3 papers, 2018 to 2021). Impairment of the renal function secondary to chronic kidney damage persisting for three or more months. "The mechanism underlying the ATF3-mediated pro-apoptotic and deleterious effect during podocyte injury under chronic kidney disease is unclear." (PMID 29038896, 2018). "For example, overexpression of ATF3 represses PTEN-induced putative kinase 1 (PINK1) gene transcription in lung epithelial cells, while ATF3/c-Jun complex stimulates cannabinoid receptor type 1 (CB1R) transcription in chronic kidney disease (CKD)." (PMID 33921748, 2021).
Cognitive impairment (3 papers, 2022 to 2025). Abnormal cognition is characterized by deficits in thinking, reasoning, or remembering. "It enhanced neuronal metabolic rebalance (Atf3‐related) and reduced neuroinflammation from a multicellular perspective, therefore improving postoperative cognitive impairment." (PMID 39540334, 2025).
diabetic neuropathy (3 papers, 2020 to 2025). A chronic, pathological complication associated with diabetes mellitus, where nerve damages are incurred due to diabetic microvascular injury involving small blood vessels that supply these nerves, resulting in peripheral and/or autonomic nerve dysfunction. "Scn3b is upregulated in nerve injuries and streptozotocin models of painful diabetic neuropathy, all of which are associated with expression of Atf3 in sensory neurons." (PMID 41322115, 2025). "Taken together, the results indicate that intraneuronal ATF3, but not CLEC5A, mediates the induction of ER stress and neuroinflammation associated with diabetic neuropathy." (PMID 34172832, 2021).
fibrosarcoma (3 papers, 2017 to 2024). A malignant mesenchymal fibroblastic neoplasm affecting the soft tissue and bone. "Interestingly, lentiviral-mediated SLC7A11 expression in ATF3 over-expressing fibrosarcoma cells restored system Xc- function and impaired ATF3-mediated ferroptosis." (PMID 38539832, 2024). "Notably, a recent study confirmed the pro-ferroptosis efficacy of ATF3 in fibrosarcoma cells." (PMID 34098867, 2021). "Notably, a recent study confirmed that ATF3 promotes ferroptosis in fibrosarcoma cells." (PMID 34098867, 2021).
Glucose intolerance (3 papers, 2019 to 2023). Glucose intolerance (GI) can be defined as dysglycemia that comprises both prediabetes and diabetes. "Both pancreatic ATF3 and pancreatic β cell-specific ATF3 transgenic mice have been found to show decreased β cell mass and severe glucose intolerance, displaying a deleterious function of ATF3." (PMID 36472556, 2023). "However, compared with control mice, conventional ATF3 knockout mice have been shown to develop more severe glucose intolerance when fed a high-fat diet due to transcriptional repression of insulin gene expression, indicating that ATF3 has a beneficial role in the pancreas." (PMID 36472556, 2023).
hepatic (3 papers, 2010 to 2018). "In the present study, we showed that ATF3 deficiency aggravated IR-induced liver inflammation by activating of mTOR/p70S6K signaling and increasing TLR4-driven inflammatory responses." (PMID 30185770, 2018). "Taken together, these data indicated that ATF3-mediated mTOR/p70S6K/HIF-1α signaling was crucial for T cell differentiation in IR-triggered liver inflammation." (PMID 30185770, 2018). "One striking finding was that ATF3 deficiency depressed Foxp3+ Tregs, whereas it increased ROR+ Th17 cells in IR-induced liver inflammation." (PMID 30185770, 2018). "Disruption of ATF3 downregulated Foxp3 and upregulated RORγt-mediated IL-17A expression in IR-induced liver inflammation." (PMID 30185770, 2018). "Importantly, rIFN-α led to increased expression of Atf3 mRNA and was sufficient to induce hepatitis as measured by ALT in Sod1−/− mice in the absence of infection." (PMID 26588782, 2015). "Furthermore, animals in the ATF3-shRNA group developed significantly more hepatic tumor nodules in liver lobes that had not been injected with tumor cells." (PMID 21129190, 2010). "Despite the known role of ATF3 in controlling innate inflammatory responses and the involvement of HIF-1α in mTOR signaling, the exact mechanisms by which ATF3 regulates innate immunity and adaptive T cell development in IR-triggered liver inflammation remain largely unknown." (PMID 30185770, 2018).
ischemia reperfusion injury (3 papers, 2019 to 2025). Adverse functional, metabolic, or structural changes in ischemic tissues resulting from the restoration of blood flow to the tissue (reperfusion), including swelling; hemorrhage; necrosis; and damage from free radicals. "In models of ischemia-reperfusion injury, ATF3 loss increases apoptosis in cardiac macrophages ex vivo and in vivo." (PMID 41198649, 2025). "Previous studies have shown that ATF3 can be detected in urine within 2-24 hours in a rat model of AKI induced by ischemia reperfusion injury and is considered a novel diagnostic biomarker for AKI." (PMID 39308866, 2024). "Such an increase in the expression of ATF3 (observed in vivo when ATF3 is overexpressed in mice by adenoviral mediated gene transfer) has been observed to result in a reduction of ischemia-reperfusion injury." (PMID 31262033, 2019).
Lewis Lung Carcinoma (3 papers, 2019 to 2022). "In mouse DCs, ATF3 expression was induced in vitro by VEGF, PGE2 and media conditioned by Lewis lung carcinoma (LLC) cells." (PMID 36333297, 2022).
Myocardial fibrosis (3 papers, 2022 to 2023). "Previous studies have shown that elevated ATF3 expression in cardiac fibroblasts can prevent adverse cardiac remodeling and suppress myocardial fibrosis induced by ischemic or hypertrophic injury." (PMID 36481938, 2022). "Consistently, infarct size and myocardial fibrosis levels were reduced in mice with ATF3 downregulation, while SPHK1 overexpression decreased the anti‐fibrotic effect of ATF3 downregulation in MI mice." (PMID 37773702, 2023). "ATF3 and SPHK1 downregulation narrowed the infarction area and attenuated myocardial fibrosis in mice, along with reduced inflammation in the serum and ER stress in the myocardium." (PMID 37773702, 2023). "Consistent with previous reports on the heart, our data confirm that ATF3, which is a key regulator that is epigenetically suppressed by KDM5B, can inhibit myocardial fibrosis mediated by cardiac fibroblasts in response to ischemic or hypertrophic stress." (PMID 36481938, 2022).
neuroblastoma (3 papers, 2011 to 2018). Neuroblastoma (NB) is the most common solid, extracranial childhood tumor. "In neuroblastoma cells, ID1 is downregulated in a hypoxic situation, but it is upregulated by HIF-1α in the absence of hypoxia-induced ATF-3." (PMID 27127787, 2016).
nonalcoholic steatohepatitis (3 papers, 2022 to 2023). "In non-alcoholic steatohepatitis (NASH) mice, hepatic ATF3 deficiency suppresses RIPK3 expression and hepatocellular death." (PMID 36690638, 2023). "Moreover, a nonalcoholic steatohepatitis (NASH)-related diet induces the collaboration of Atf3 with LXRs to induce Trem2 and Cd9 expression, promoting the establishment of the SAM and/or LAM phenotypes." (PMID 35359989, 2022). "Previous reports have indicated that ATF3 plays a protective role in the progression of high-fat diet-induced nonalcoholic fatty liver (NAFL) and nonalcoholic steatohepatitis (NASH) through inhibition of liver inflammation, hepatocellular apoptosis, hepatic stellate cell activation, and fibrosis." (PMID 36472556, 2023).
oral cancer (3 papers, 2008 to 2020). "Our initial description of the BK5.ATF3 mouse model reported a high incidence (~70%) of oral carcinomas in older transgenic mice of both genders, and was the first evidence clearly suggesting that ATF3 may act as an oncogene." (PMID 18808719, 2008).
pneumonia (3 papers, 2022 to 2025). An acute, acute and chronic, or chronic inflammation focally or diffusely affecting the lung parenchyma, caused by an infection in one or both of the lungs (by bacteria, viruses, fungi, or mycoplasma.). "In pneumonia caused by Streptococcus pneumoniae, ATF3 positively regulates the innate immunity during pneumococcal infection by enhancing TNF‐α, IL‐1β, and IFN‐γ expression and controlling bacterial clearance." (PMID 37773692, 2023). "In pneumonia caused by Staphylococcus aureus, ATF3 regulates the expression of intracellular antimicrobial genes, actin cytoskeleton, and the cell migration of macrophages to ameliorate inflammation." (PMID 37773692, 2023). "Meanwhile, ATF3 KO mice were more susceptible to S. aureus infection, had a higher bacterial load, and experienced exacerbated pneumonia tissue damages." (PMID 35370996, 2022). "Since macrophages and neutrophils are critical to the survival of pneumonia, we investigated whether the loss of ATF3 affects the recruitment of macrophages or neutrophils to the alveolar space during S. aureus pneumonia." (PMID 35370996, 2022). "This suggests that ATF3 has a protective function against lethal S. aureus pneumonia and limits the host bacterial load." (PMID 35370996, 2022). "In this study, we showed that infection with S. aureus significantly increased ATF3 expression, which accelerated bacterial clearance and could reduce the symptoms of pneumonia in mice." (PMID 35370996, 2022).
retinal degeneration (3 papers, 2018 to 2025). Degeneration of the retina. "Through protein–protein interaction (PPI) network analysis, six hub ferroptosis-related genes (Jun, Stat3, Hmox1, Atf3, Hspa5 and Ripk1) are ultimately identified in a mice model of retinal degeneration induced by light damage." (PMID 40299661, 2025). "In the retina, ATF3 protected against ganglion cell death in crush models and was identified in survival pathways in the rd10 retinal degeneration mouse model." (PMID 35337132, 2022). "In order to test the effects of ATF3 on AChE, in vivo, we chose the mouse model of photic-stress-induced retinal degeneration, which we previously used to show the upregulation of AChE in photoreceptors apoptosis." (PMID 29681794, 2018).
Streptococcus pneumoniae infection (3 papers, 2018 to 2023). "Given that ATF3 also plays an important role in NLRP3 inflammasome-dependent IL-1β secretion, these data support the idea that ATF3 is an important inflammatory factor in early pneumococcal infection." (PMID 30214444, 2018). "For instances, macrophages ATF3 plays key roles in host survival and pathogen clearance through controlling intracellular calcium level and ATP homeostasis, and consequently stimulating interleukin 17A (IL-17A) expression during streptococcus pneumoniae infection." (PMID 37645012, 2023).
thyroid cancer (3 papers, 2024 to 2025). "ATF3 overexpression has been linked to altered DUSP expression in other cancer models, including thyroid cancer." (PMID 41198649, 2025). "The overexpression of ATF3 in 8305 C thyroid cancer cells significantly decreased cell viability and induced apoptosis and cell cycle arrest in vitro." (PMID 39085957, 2024). "Further, this reduction in ATF3 expression likely contributes to the progression of thyroid cancer by directly regulating prognostic genes within the MAPK and PI3K/AKT pathways." (PMID 39085957, 2024). "ATF3 is a hypoxia-associated gene biomarker for OSA and acts as a tumor suppressor in thyroid cancer." (PMID 39719972, 2024).
abdominal aortic aneurysm (2 papers, 2023 to 2025). Enlargement and ballooning of the vessel that supplies arterial blood to the abdomen, pelvis and legs. "To further validate ATF3's involvement in AAD progression, we assessed aortic diameter differences between Atf3 cKO mice and their control littermates using a PPE‐induced abdominal aortic aneurysm (AAA) model, in which PPE degrades elastic fibres, causing aortic damage and aneurysm development." (PMID 39731276, 2025).
adrenal carcinoma (2 papers, 2015 to 2020). A carcinoma involving a adrenal gland. "Previous reports have demonstrated that ATF3 is expressed in H295R human adrenal carcinoma cells and may be involved in adrenocortical aldosterone synthesis." (PMID 32093223, 2020).
Alzheimer disease (2 papers, 2014 to 2022). A progressive, neurodegenerative disease characterized by loss of function and death of nerve cells in several areas of the brain leading to loss of cognitive function such as memory and language. "Previous studies have shown up-regulation of ATF3 to act as either pro-inflammatory or anti-inflammatory and it was more recently linked to Alzheimer’s disease through a system-level approach." (PMID 24993133, 2014).
cardiomyopathy (2 papers, 2025). A disease of the heart muscle or myocardium proper. "Genetic ablation of Atf3 in FS6KD corroborated its pivotal role, effectively delaying cardiomyopathy progression in a female-specific manner." (PMID 40184463, 2025).
Cirrhosis (2 papers, 2023). A chronic disorder of the liver in which liver tissue becomes scarred and is partially replaced by regenerative nodules and fibrotic tissue resulting in loss of liver function. "In the same manner, associated with cirrhosis risk rs11119982 (ATF3) C allele creates one unique TFBS for the helicase-like transcription factor (HLTF) which is involved with altering chromatin structure." (PMID 37059745, 2023). "However, cirrhosis was more prevalent in individuals with the GADD45A rs532446 TT and ATF3 rs11119982 TT genotypes." (PMID 37059745, 2023).
Crohn disease (2 papers, 2018 to 2024). A gastrointestinal disorder characterized by chronic inflammation involving all layers of the intestinal wall, noncaseating granulomas affecting the intestinal wall and regional lymph nodes, and transmural fibrosis. "Clinical correlation of ATF3 in IBD has been reported, with ATF3 expression being significantly upregulated in patients with Crohn's disease." (PMID 30455690, 2018).